RFK (riboflavin kinase)
Description:
Catalyzes the phosphorylation of riboflavin (vitamin B2) to form flavin-mononucleotide (FMN), hence rate-limiting enzyme in the synthesis of FAD. Essential for TNF-induced reactive oxygen species (ROS) production. Through its interaction with both TNFRSF1A and CYBA, physically and functionally couples TNFRSF1A to NADPH oxidase. TNF-activation of RFK may enhance the incorporation of FAD in NADPH oxidase, a critical step for the assembly and activation of NADPH oxidase.
Synonyms: FLJ11149; RIFK
Tractability: Small molecule: a structure with a bound ligand is known; it has a high-quality binding pocket. PROTAC: ubiquitination databases record sites on it; its protein half-life has been measured.
Gene: Protein-coding gene on chromosome 9 (76,385,526 to 76,394,517, reverse strand). Ensembl gene ENSG00000135002.
Subcellular location: Cytoplasm
Subcellular location (Human Protein Atlas): Golgi apparatus
Pathways (Reactome):
Metabolism: Vitamin B2 (riboflavin) metabolism
Gene Ontology:
Molecular function: protein binding; riboflavin kinase activity
Biological process: apoptotic process; positive regulation of NAD(P)H oxidase activity; riboflavin metabolic process; FMN biosynthetic process; riboflavin biosynthetic process
Cellular component: Golgi apparatus; mitochondrion; cytoplasm; cytosol
Genetic constraint (gnomAD): Loss-of-function variants: 1 observed, 8.51 expected, observed/expected ratio (o/e) 0.12, 90% interval 0.041 to 0.56. That is too few expected variants to judge how well the gene tolerates losing a copy. Missense variants: 110 observed, 111.14 expected, observed/expected ratio (o/e) 0.99, 90% interval 0.85 to 1.16. Synonymous variants: 42 observed, 37.4 expected, observed/expected ratio (o/e) 1.12, 90% interval 0.88 to 1.45.
Homologues: Orthologues: chimpanzee RFK (100% identical), macaque RFK (98% identical), dog RFK (95% identical), guinea pig RFK (95% identical), mouse Rfk (94% identical), rat Rfk-ps1 (94% identical), rat AABR07053065.1 (92% identical), rat Rfk (91% identical), zebrafish rfk (75% identical), tropical clawed frog rfk (73% identical), Drosophila melanogaster Rfk (59% identical), pig RFK (58% identical), and 1 more.
Diseases named in the same sentence as RFK in open-access papers:
RFK is named in the same sentence as 21 diseases in open-access papers, as found by Europe PMC text mining. Sharing a sentence is not in itself a finding about the gene and the disease. The quoted sentences say what the papers report.
cognitive decline (3 papers, 2023 to 2025). "Though pathogenic RFK mutations are rare, animal models have shown that RFK loss results in impaired mitochondrial electron transport, NF-κB activation, cognitive decline, and neuroinflammation, highlighting its disease relevance." (PMID 40963932, 2025). "RFK overexpression abolished the effects of FMN in inhibiting inflammation induced cognitive decline." (PMID 40175896, 2025). "To address how riboflavin metabolism acts on microglial function in cognitive decline, we examined the expression pattern of RFK in neural cells." (PMID 36799538, 2023).
Stroke (2 papers, 2013 to 2025). Sudden impairment of blood flow to a part of the brain due to occlusion or rupture of an artery to the brain. "Can riboflavin supplementation improve the susceptibility to stroke caused by RFK gene dysfunction and thereby prolong the survival cycle?" (PMID 40175896, 2025). "RFK deserves further investigation as a promising target gene for the detection of stroke susceptibility." (PMID 40175896, 2025). "One factor that showed reduced expression in SHRSP rats was a riboflavin kinase which was subsequently identified as a new potential risk factor for stroke." (PMID 24024100, 2013). "Since RFK is a catalytic enzyme for the transformation of riboflavin in the body, the utilization of riboflavin by the body’s cells is first affected by the RFK gene dysfunction; If RFK gene dysfunction increases the susceptibility to stroke, is it because the decreasing utilization of riboflavin?" (PMID 40175896, 2025). "RFK deserves further investigation as a promising target gene for stroke susceptibility detection." (PMID 40175896, 2025). "Among the reports on the effect of riboflavin in the pathogenesis of stroke, the interaction between riboflavin and serum homocysteine was mostly followed; but there has been no report linking the riboflavin protective role in stroke with RFK gene dysfunction." (PMID 40175896, 2025). "Taken together, our results suggest that RFK inhibit ischemic brain damages, and thus may be explored as a promising preventive and therapeutic target for stroke." (PMID 40175896, 2025).
acute myocardial infarction (1 paper, 2024). Necrosis of the myocardium, as a result of interruption of the blood supply to the area. "A case–control study compared biochemical markers of 30 patients having acute myocardial infarction with 30 healthy people, and found that riboflavin kinase levels were substantial increased in patients with acute myocardial infarction." (PMID 39726878, 2024).
breast invasive carcinoma (1 paper, 2023). "RFK is essential for TNF-induced ROS production, which can influence the progress of breast invasive carcinoma and human prostate cancer." (PMID 37223030, 2023).
Cerebral ischemia (1 paper, 2025). Restriction of arterial blood supply to the brain associated with insufficient oxygenation to support the metabolic requirements of the tissue. "In conclusion, we have demonstrated that RFK is an endogenous protein against ischemic brain injury, and that RFK inhibits the area of infarction, oedema and neuronal apoptosis after cerebral ischemia." (PMID 40175896, 2025). "We demonstrated that RFK was an endogenous protein against ischemia brain injury both in vivo and in vitro experiments." (PMID 40175896, 2025).
Cognitive impairment (1 paper, 2023). Abnormal cognition is characterized by deficits in thinking, reasoning, or remembering. "Here, we reported for the first time that RFK is expressed in the microglia and that it is upregulated in the cortex and hippocampus of the LPS‐induced mouse model and 5xFAD mouse model of AD, suggesting that it may be related to inflammation‐based cognitive impairment." (PMID 36799538, 2023).
ischemia (1 paper, 2025). A hypoperfusion of the BLOOD through an organ or tissue caused by a PATHOLOGIC CONSTRICTION or obstruction of its BLOOD VESSELS, or an absence of BLOOD CIRCULATION. "The present study demonstrates that RFK is an important regulatory molecule against ischemia brain injury and its mechanism involves inhibition of ERS." (PMID 40175896, 2025).
ischemic stroke (1 paper, 2025). A stroke disorder caused by obstruction of blood flow to the brain, due to thrombotic (local blood clot formation) or embolic (due to a blood clot or other material traveling from another site) event. "Dysfunction of the RFK gene has been associated with susceptibility to ischemic stroke." (PMID 40175896, 2025). "Our previous study showed that RFK gene dysfunction may be associated with susceptibility to ischemic stroke." (PMID 40175896, 2025). "However, the specific mechanism of the role of RFK in ischemic stroke remains to be investigated." (PMID 40175896, 2025). "However, the protective role and mechanisms of RFK in ischemic stroke have not been elucidated." (PMID 40175896, 2025).
lung adenocarcinoma (1 paper, 2022). A carcinoma that arises from the lung and is characterized by the presence of malignant glandular epithelial cells. "Similarly, the lower expression of GABARAPL1 and RFK was associated with improved OS in lung adenocarcinoma patients." (PMID 35574381, 2022).
pancreatic tumor (1 paper, 2023). "However, the role of COQ4, MCRIP2, MRPL50, MRPL14, RFK, and NMNAT3 in pancreatic tumor has not been reported." (PMID 37223030, 2023).
Parkinson disease (1 paper, 2025). A progressive degenerative disorder of the central nervous system characterized by loss of dopamine producing neurons in the substantia nigra and the presence of Lewy bodies in the substantia nigra and locus coeruleus. "RFK is required for 4, 4’-dimethoxychalcone mediated neuroprotection in Parkinson’s disease (PD) mouse models, and reduction of RFK may be related to PD pathogenesis." (PMID 40175896, 2025).
infection (2 papers, 2021 to 2025). The state of being infected such as from the introduction of a foreign agent such as serum, vaccine, antigenic substance or organism. "Further studies, including groups of uninfected control animals, should particularly focus on the expressions of GBP7, RFK, IRF4, and EPHA3 at several time points following infection." (PMID 33918448, 2021).
RFK also shares sentences with these, for which no sentence is quoted: Alzheimer disease (1 paper); brain inflammation (1); brain injury (1); breast carcinoma (1); diabetes (1); myocardial ischemia (1); prostate carcinoma (1); tumor (1); Type 2 diabetes (1).